CCR3 (C-C motif chemokine receptor 3)
Diseases named in the same sentence as CCR3 in open-access papers (continued):
Sharing a sentence is not in itself a finding about the gene and the disease.
renal carcinoma (3 papers, 2020 to 2022). A carcinoma arising from the epithelium of the renal parenchyma or the renal pelvis. "CCR3 expression in tumor tissues has been also shown to correlate with the grade of malignancy in human renal cancer." (PMID 34206004, 2021).
T-cell lymphomas (3 papers, 2016 to 2022). "Expression of receptor CCR3 or CCR10 is elevated in the inflammatory process and T-cell lymphoma." (PMID 36016177, 2022).
airway allergies (2 papers, 2016 to 2024). "Therefore, CCR3 may be a target gene for the study of respiratory allergic diseases." (PMID 38212473, 2024).
Chronic colitis (2 papers, 2015 to 2022). A chronic inflammatory disease of the large intestine (colon, cecum and rectum). "In chronic colitis, we found both populations among colonic lamina propria leukocytes (cLPL), with high granularity (SSChi) and expression of the eotaxin receptor CCR3 confirming them as eosinophils." (PMID 26200014, 2015). "The chemokine receptor, CCR3 which plays a role in the recruitment and activation of eosinophils has been shown that its blockade via a CCR3 antagonist attenuates disease severity and morphological damage to inflamed intestinal tissues in the spontaneous model of chronic colitis (Winnie mice)." (PMID 36551617, 2022).
cognitive decline (2 papers, 2022 to 2024). "Increased expression of CCR3 and its ligands (CCL5, CCL11, and CCL24) are also associated with cognitive decline associated with aging." (PMID 38332938, 2024). "Elevated CCL11 in the plasma and cerebrospinal fluid seen in aging mice and humans are associated with declining neurogenesis, neurodegenerative disease, and cognitive decline and may contribute to driving neovascularisation in AMD via interaction with CCR3." (PMID 35501923, 2022).
cognitive deficits (2 papers, 2023 to 2024). "To further assess a critical role for CCR3, we tested CCL24, another ligand which increases with age, and found that administration of recombinant CCL24 also induced cognitive deficits." (PMID 36934154, 2023).
cutaneous T cell lymphoma (2 papers, 2017 to 2025). "In Hodgkin lymphoma and cutaneous T cell lymphoma (CTCL), CCL26 recruits CCR3+ T lymphocytes into TIME, where they secrete high levels of IL-4—a hallmark of a T helper 2 (Th2)-dominant microenvironment that is closely associated with CTCL development." (PMID 41280721, 2025).
fibrosis (2 papers, 2023 to 2024). the formation of excess fibrous connective tissue in an organ or tissue in a reparative or reactive process. "Previous studies have shown that both CCL24 and CCR3 are involved in skin and lung inflammation and fibrosis." (PMID 38267432, 2024). "Higher levels of CCL24 and CCR3 were found in the skin and sera of patients with SSc compared with healthy controls; elevated levels of CCL24 and CCR3 were associated with fibrosis and predictive of greater lung function deterioration." (PMID 37555717, 2023).
head and neck cancer (2 papers, 2022 to 2024). A primary or metastatic malignant neoplasm affecting the head and neck. "Expression of CCL11 and CCR3 promotes tumor aggressiveness in head and neck cancer." (PMID 38305920, 2024).
infarction (2 papers, 2015 to 2017). A localised pathological necrosis of tissue resulting from obstruction of the blood supply usually by a thrombus, an embolus, or vascular torsion. "Links between neuronal cell survival and CCR3 have been described: Ccr3-expressing CD4+ T cells are necessary for facial motoneuron survival after facial nerve axotomy, whereas CCR3 promotes neuronal cell death in a post-infarction mouse model." (PMID 29186205, 2017). "Isolated-heart Langendorff perfusion showed no significantly differences in heart function, infarction size and post infarction angiogenesis after CCR3 blockade." (PMID 32309568, 2015).
liver cancer (2 papers, 2024 to 2025). An epithelial or non-epithelial malignant neoplasm that arises from the liver. "Through their interaction with specific receptors, such as CCR1, CCR2, CCR3, etc., these chemokines play a crucial role in the evolution of liver cancer." (PMID 40062588, 2025).
lupus (2 papers, 2021 to 2025). "CCR3 expression is also found to be increased in lupus patients with renal damage and positively resulted in more inflammation." (PMID 35317107, 2021). "In the present study, we investigated the expression of chemokine receptors, CXCR3, CCR5, CCR4, and CCR3, in the surface of probiotic-maturated tolerogenic DCs (matured by L. rhamnosus and L. delbrueckii) with monocyte origin to find the effect of these probiotics on migratory lupus-DC patterns." (PMID 35317107, 2021).
neuropathic pain (2 papers, 2021 to 2022). Chronic pain caused by damage to nerve fibers. "In light of our research, we propose that CCL2/7/8/CCR1 and CCL7/8/CCR3 signaling are important elements in the modulation of neuropathic pain." (PMID 36611891, 2022). "Therefore, we postulate that CCR3-targeted therapy will be beneficial to patients since its antagonist positively influences neuroimmune interactions by modulating MPO+ cell activation and influx in neuropathic pain." (PMID 34795678, 2021).
neuropathy (2 papers, 2021 to 2022). A disorder affecting the nervous system that manifests with pain, tingling, numbness, and/or muscle weakness. "We found these receptors interesting to study because, to the best of our knowledge, there are only a few studies concerning CCR1 in neuropathy, and there is only one previously published study (by us) on CCR3 involvement in neuropathy." (PMID 36611891, 2022). "We observed for the first time that UCB35625 (CCR1/CCR3 antagonist) inhibits pain-like behavior, without influencing the motor dysfunction observed in neuropathy, which confirms its analgesic effectiveness." (PMID 36611891, 2022).
thyroid cancer (2 papers, 2020 to 2024). "According to transcriptome sequencing, antitumor chemokine regulatory genes (CXCR3) were upregulated, and protumor chemokine regulatory genes (CCR3, CXCL1, CXCL2, CXCL3, CXCL8, and CXCR2) were downregulated after MWA in thyroid cancer." (PMID 38779358, 2024).
triple-negative breast carcinoma (2 papers, 2022). An invasive breast carcinoma which is negative for expression of estrogen receptor (ER), progesterone receptor (PR), and human epidermal growth factor receptor 2 (HER2). "For patients with triple negative breast cancer, CCR3 was higher in Black versus White and CCRL2 was higher in Asian versus White." (PMID 35754051, 2022).
abortion (1 paper, 2019). the ending of pregnancy by removing a fetus or embryo before it can survive outside the uterus. "CCL28 has been found to induce apoptosis in decidual stromal cells, and a higher expression of the receptors of CCL28 (CCR3, CCR10), in these cell populations in spontaneous abortion is displayed prior to a pro-inflammatory stimulation." (PMID 30755659, 2019).
Acinetobacter infection (1 paper, 2024). "A reduction of neutrophil accumulation was also observed in the BAL and lung of Ccl28−/− mice during Acinetobacter infection, with neutrophils recruited to the lung harboring surface CCR3 and CCR10." (PMID 39193987, 2024).
allergic conjunctivitis (1 paper, 2014). "The role of CCR3 in allergic conjunctivitis has been previously demonstrated in mice subjected to allergic sensitization." (PMID 24916929, 2014).
amyloid (1 paper, 2018). "Yet, CCR3 and CCR5 are predominantly found in microglia of both control and AD brains, expressing reactive microglia, and MIP-1β expression (ligands for CCR5 and/or CCR3) of reactive astrocytes were seen to be associated with amyloid deposits." (PMID 30186116, 2018).
astrocytoma (1 paper, 2020). "The astrocytoma/glioblastoma cell line also up-regulates CCR3 and CCR5 expression following morphine treatment." (PMID 32076421, 2020). "Morphine administration induces the expression of CCR3, CCR5, and CXCR2 in the U87 human astrocytoma cell line." (PMID 32076421, 2020).
Autoimmunity (1 paper, 2022). The occurrence of an immune reaction against the organism's own cells or tissues. "Finally, C–C Motif Chemokine Receptor 3 (CCR3) region (3p21), already linked to familiarity of autoimmunity among children with type I diabetes, has been recently associated with CD and JIA." (PMID 35459143, 2022).
bladder cancer (1 paper, 2022). "Concurrently, SKA3 expression was positively correlated with the expression level of Th2 cell markers (IL-4 and CCR3) in bladder cancer." (PMID 35546682, 2022). "In addition, SKA3 expression in bladder cancer was significantly correlated with M2 macrophage markers, including MRC1 and CD163, and Th2 cell markers, including CCR3 and IL-4." (PMID 35546682, 2022).
celiac disease (1 paper, 2009). An autoimmune genetic disorder with an unknown pattern of inheritance that primarily affects the digestive tract. "Noteworthy is that IL18RAP and CCR3, both recently identified as being genetically associated with celiac disease, exhibited significant cis-regulation in the celiac peripheral blood dataset but not in the HapMap B cell line dataset." (PMID 19128478, 2009).
cerebral malaria (1 paper, 2005). A sequestration of Plasmodium falciparum in the brain, which can cause coma and/or seizures. "In this study, the expressions of RANTES and its corresponding receptors CCR1, CCR3 and CCR 5 were up-regulated in the brain during P. yoelii 17XL infection, further implicating these molecules in the pathogenesis of rodent cerebral malaria." (PMID 16359553, 2005).
cholangiocarcinoma (1 paper, 2017). A carcinoma that arises from the intrahepatic biliary tree (intrahepatic cholangiocarcinoma) or from the junction, or adjacent to the junction, of the right and left hepatic ducts (hilar cholangiocarcinoma). "In our present study, MSCs under inflammatory condition exhibited higher expression levels of CCL5 than control MSCs cells, and co-culture of cholangiocarcinoma cells with MSC(TI)-CM induced upregulation of CCR1, CCR3 and CCR5 expression." (PMID 29088737, 2017).
chondrosarcoma (1 paper, 2011). A malignant cartilaginous matrix-producing mesenchymal neoplasm arising from the bone and soft tissue. "The eotaxin-1 receptor CCR3 expressed on SW1353 chondrosarcoma cells belongs to the family of G protein-coupled receptors." (PMID 22114952, 2011). "The production of eotaxin-1 not only induces expression of its own receptors, CCR3 and CCR5, on the cell surface of chondrosarcomas, but also markedly increases the expression of MMP-3 mRNA in chondrocytes." (PMID 22114952, 2011).
choroidal neovascularization (1 paper, 2016). An eye disorder described by the growth of new blood vessels that originate from the choroid through a break in the Bruch membrane into the sub–retinal pigment epithelium (sub-RPE) or subretinal space. "We assessed the effects of CCR3 inhibition on retina and choroidal endothelial cells (CECs) that develop into choroidal neovascularization (CNV)." (PMID 27309355, 2016).
chronic GVHD (1 paper, 2014). "The molecules that provided the best discrimination between acute and chronic GVHD were: the activation marker CD9; adhesion molecules CD11c and CD18; chemokine receptor CCR3; and prostaglandin receptor CRTH2." (PMID 25400930, 2014).
dementia (1 paper, 2022). Loss of intellectual abilities interfering with an individual's social and occupational functions. "In addition to changes in cell-cell signaling pathways, the CCR3 pathway was upregulated, which has been identified as a possible driver of viral-induced dementia and a key mediator of neuronal death." (PMID 36408415, 2022).
Depression (1 paper, 2012). "The One Carbon Pool by Folate, Long-term Potentiation, Long-term Depression, and CCR3 Signaling in Eosinophils pathways are potentially hi-jacked processes suppressed in the Early Phase." (PMID 22912686, 2012).
diarrhoea (1 paper, 2022). "Other DEGs that were down-regulated in the high-diarrhoea group include Ovar-DRB1, DQA, TREM2, TFF3, ITLN2, CD74, CCL5, and CCR3." (PMID 35140270, 2022).
dilated cardiomyopathy (1 paper, 2023). Cardiomyopathy which is characterized by dilation and contractile dysfunction of the left and right ventricles. "Then, we performed a GSEA analysis; we found that the CCR3 inhibitor group was negatively related to cell division, cell adhesion, dilated cardiomyopathy, and hypertrophic cardiomyopathy." (PMID 36131165, 2023).
drug allergy (1 paper, 2025). Immunologically mediated adverse reactions to medicinal substances used legally or illegally. "On the other hand, the proportion of CCR3+ PBMC decreased in peripheral blood of AA and ARA− patients in the current study, which is an unexpected result since enhanced expression of CCR3+ basophils has been noticed in allergic conditions such as food, grass pollen and drug allergy." (PMID 40534099, 2025).
ductal breast carcinoma (1 paper, 2019). "Using tissue data we found that CCL11 (Eotaxin), which has a high affinity for CCR3, was higher in ductal breast carcinoma tissues when compared to healthy controls and other histological tissue types." (PMID 30850664, 2019).
Dysmenorrhea (1 paper, 2022). Pain during menstruation that interferes with daily activities. "The purpose of this study is to investigate whether eotaxin/CC chemokine receptor 3 (CCR3) axis, a key regulatory pathway for eosinophils (EOS) recruitment, is involved in acupuncture analgesia for dysmenorrhea." (PMID 35069759, 2022).
endothelial dysfunction (1 paper, 2024). In vascular diseases, endothelial dysfunction is a systemic pathological state of the endothelium (the inner lining of blood vessels) and can be broadly defined as an imbalance between vasodilating and vasoconstricting substances produced by (or acting on) the endothelium. "CCR3 is involved in several other diseases in which endothelial dysfunction is associated with pathogenesis, and it has been successfully targeted as a treatment for these conditions." (PMID 38332938, 2024). "The expression of C-C motif chemokine receptor 3 (CCR3) is associated with endothelial dysfunction and memory impairment." (PMID 38332938, 2024). "This study aims to show that CCR3 expression in this rodent model that mimics thrombectomy is associated with endothelial dysfunction that is a characteristic of VCID." (PMID 38332938, 2024). "CCR3 and its ligands have been implicated in the process of endothelial dysfunction in a variety of diseases." (PMID 38332938, 2024). "Our results revealed promising support of an animal model that CCR3 signaling is related to endothelial dysfunction." (PMID 38332938, 2024). "CCR3 and its inflammatory pathway is a potential target for reducing endothelial dysfunction after ischemic stroke that may lead to VCID." (PMID 38332938, 2024).
Gastrointestinal inflammation (1 paper, 2023). Inflammation of the alimentary part of the gastrointestinal system. "Interestingly, in models of skin, lung, or gastrointestinal inflammation, CCR3+ T lymphocytes are recruited together with eosinophils, again suggesting an interaction between these cell types in disease." (PMID 36934154, 2023).
glaucoma (1 paper, 2017). Increased pressure in the eyeball due to obstruction of the outflow of aqueous humor. "To quantitatively compare changes in expression profiles of CCR3 and CCR5 associated with glaucoma-related stressors, we measured the thresholded Mander's split co-localization coefficients of CCR3 and CCR5 with Brn3a and GSyn in each condition." (PMID 28936366, 2017). "To determine whether glaucoma-related stressors alter expression of CCL5 signaling machinery, we examined protein expression and localization of CCL5, CCR5 and CCR3 in retina from age-matched C57Bl/6and DBA/2 mice." (PMID 28936366, 2017).
glomerulonephritis (1 paper, 2022). A renal disorder characterized by damage in the glomeruli. "Similar to our findings, increased expression of RANTES, a ligand for the chemokine receptors CCR1, CCR3, and CCR5, has been observed in vivo in various inflammatory diseases, including adjuvant-induced arthritis, glomerulonephritis, granulomatous inflammation, and OP." (PMID 35270014, 2022).
Granuloma (1 paper, 2011). A compact, organized collection of mature mononuclear phagocytes, which may be but is not necessarily accompanied by accessory features such as necrosis. "Overall this study suggests that CCL2 and CCL5 may be interacting with mononuclear cells expressing specific CC chemokines receptors (CCL2 → CCR2, CCL5 → CCR1, CCR3, and CCR5) and are important biologically in the formation of pulmonary sarcoidosis granulomas." (PMID 21463523, 2011). "We found that epithelioid histocytes, macrophages and infiltrating lymphocytes that form the pulmonary sarcoid non-necrotizing granuloma were all expressing CCR1 and CCR3." (PMID 21463523, 2011).
granulomatosis with polyangiitis (1 paper, 2012). A small-vessel necrotizing vasculitis characterized by the association of inflammation of the vessel wall and peri- and extravascular granulomatosis. "Previously, small proportions of circulating Th1-type CCR5+ and Th2-type CCR3+ cells have been shown in granulomatosis with polyangiitis (GPA)." (PMID 22490506, 2012). "Previously, we showed that a small proportion of circulating memory T cells displays T-helper cell 1 (Th1)-type CC chemokine receptor (CCR) 5 and Th2-type CCR3 expression in granulomatosis with polyangiitis (GPA)." (PMID 22490506, 2012).
Graves disease (1 paper, 2016). Graves' disease is an autoimmune disorder that leads to overactivity of the thyroid gland (hyperthyroidism).It is caused by an abnormal immune system response that causes the thyroid gland to produce too much thyroid hormones. "They concluded that RANTES (regulated on activation, normal T cells expressed and secreted) in interaction with its receptors (CCR1, CCR3, CCR4, and CCR5), mainly on the lymphocytes, may be involved in the maintenance of lymphocytic infiltration and the autoimmune responses in Graves' disease." (PMID 27872865, 2016).
heart failure (1 paper, 2023). Inability of the heart to pump blood at an adequate rate to meet tissue metabolic requirements. "These bioinformatics results are highly consistent with our molecular biology results; therefore, we can verify the participation of the CCL24/CCR3 axis in the pathology of heart failure and cardiac fibrosis." (PMID 36131165, 2023). "CCL24/CCR3 axis plays a crucial role in the pathological development of cardiac remodeling during heart failure induced by Ang II." (PMID 36131165, 2023). "We demonstrated firstly that CCL24 /CCR3 axis is involved in cardiac remodeling during the pathology of heart failure." (PMID 36131165, 2023). "First of all, we just only verify the role of the CCL24/CCR3 axis in heart failure with monoclonal blocking antibody; however, we do not verify it with transgenic mice." (PMID 36131165, 2023). "Therefore, we speculated that CCL24/CCR3 is involved in cardiac remodeling during heart failure, and we planned to investigate the role and mechanism of the CCL24/CCR3 axis in Ang II–induced heart failure." (PMID 36131165, 2023).
Hepatic steatosis (1 paper, 2025). Steatosis is a term used to denote lipid accumulation within hepatocytes. "Their findings reveal that the CCL11/CCR3 axis drives macrophage-mediated inflammation and hepatic steatosis, while the genetic ablation of CCL11 or a pharmacological CCR3 blockade significantly attenuates ALD progression." (PMID 40429807, 2025).
hypertrophic cardiomyopathy (1 paper, 2023). A condition in which the myocardium is hypertrophied without an obvious cause. "Furthermore, according to our bulk RNA-seq result, CCL24/CCR3 axis was negatively related to muscle contraction, cardiac muscle contraction, heart contraction, and hypertrophic cardiomyopathy and immune and inflammatory response." (PMID 36131165, 2023).